SPARC (secreted protein acidic and cysteine rich)
Diseases named in the same sentence as SPARC in open-access papers (continued):
Sharing a sentence is not in itself a finding about the gene and the disease.
tumor (continued). "SPARC was up-regulated in Barrett’s-associated adenocarcinoma and promoted tumor development." (PMID 29262657, 2017). "SPARC expression is associated with tumor metastasis and poor prognosis in several types of cancer." (PMID 28718842, 2017). "SPARC is also expressed in many advanced cancers and associated with tumor migration and invasion." (PMID 29262657, 2017). "Identification of a specific pattern of expression of miRNAs in SPARC expressed cells could shed light on the underlying mechanisms of SPARC mediated tumor suppressive and chemosensitising effects." (PMID 28435518, 2017). "In PDAC, SPARC signaling appears to be associated with tumor growth suppression in vitro." (PMID 28486750, 2017). "SPARC also appeared in neovascular endothelial cells and a few tumor-associated macrophages." (PMID 29156791, 2017). "SPARC also appeared neovascular endothelial cells and a few tumor-associated macrophages." (PMID 29156791, 2017). "In normal healthy individuals, cerebral endothelial cells reside in plasma concentrations of SPARC between 0.1 and 0.8 μg/ml, while increased concentrations have been associated with pathological conditions such as neoplasia, trauma, heart, and kidney diseases." (PMID 27581191, 2016). "In contrast, in MI disease, the expression of SPARC exhibited distinctive compartmentalization with decrease in the frequency and intensity of staining in the cancerous tissue while positive staining was mainly observed in the tumor associated stroma." (PMID 27564266, 2016). "Interestingly, SPARC has been found to be highly expressed in malignant cells and stromal cells associated with neoplasia." (PMID 25161624, 2014). "Although SPARC overexpression is associated with tumor progression and poor prognosis, targeted therapy using nab-paclitaxel may improve outcomes in these patients." (PMID 25202467, 2014). "Hence, elucidation of the mechanisms underlying SPARC-mediated tumor suppression and the numerous confounding factors have been investigated in order to develop therapeutic strategies to confront cancer growth and metastasis." (PMID 23123816, 2013). "Indeed, several genes implicated in tumor-stromal interactions and induced in CAFs by coculture with cancer cells, such as SPARC, COX-2 and matrix-metalloproteinases (MMPs) are regulated by DNA methylation." (PMID 22984426, 2012). "It is therefore tempting to speculate based on the present results and our studies in SPARC-deficient animals that SPARC is a central control point for regulation of TGFβ activity in the tumor microenvironment." (PMID 22348081, 2012). "Therefore, we developed SPARC promoter-based CRAds since the SPARC gene is expressed both in malignant cells and in tumor-associated stromal cells." (PMID 19337591, 2009). "Moreover, the tumor-specific uptake of exogenous albumin can be explained by receptor-mediated albumin uptake pathways related to albumin binding proteins such as membrane-associated glycoprotein and secreted protein acidic and rich in cysteine (SPARC)." (PMID 38791347, 2024). "Therefore, SPARC is associated with GC progression and poor survival of patients, which could be useful markers to predict tumor progression." (PMID 38021154, 2023). "Additionally, the tumor-specific uptake of albumin can also be explained by receptor-mediated albumin uptake pathways involved with albumin binding proteins such as membrane-associated glycoprotein and secreted protein acidic and rich in cysteine (SPARC)." (PMID 36614318, 2023). "In addition, SPARC has been associated with tumor suppression." (PMID 36830573, 2023). "Moreover, SPARC is associated with clinicopathological parameters such as histological differentiation, tumour size, depth of invasion, lymph node metastasis, distant metastasis, and Tumor-Node-Metastasis (TNM) stage." (PMID 26703564, 2015).
tumor (continued). "Gp60 facilitates transcytosis of albumin across the endothelium, while SPARC binds and retains albumin within the tumor microenvironment, increasing the specificity of its cellular uptake and drug delivery." (PMID 41489768, 2026). "A 9-kDa matricellular SPARC fragment released by CTSD displays pro-tumor activity in the TNBC microenvironment." (PMID 41399382, 2026). "This review synthesizes evidence on the roles and molecular mechanisms of major myokines-including IL-6, irisin, SPARC, oncostatin M (OSM), and decorin-in exercise-associated modulation of cancer-related inflammation and tumor progression." (PMID 41983081, 2026). "Secreted protein acidic and rich in cysteine (SPARC) is an ECM protein that contributes to tumor progression and metastasis." (PMID 41532367, 2026). "The interaction of albumin with receptors that are overexpressed in TNBC tissues, such as gp60 and SPARC, allows for active targeting and transcytosis of drug-loaded nanoplatforms to tumor locations." (PMID 41489768, 2026). "CAFs upregulate genes involved in extracellular matrix (ECM) synthesis, including SPARC (Secreted Protein Acidic and Rich in Cysteine), whose components, such as type 1 collagen, promote tumor growth and metastasis." (PMID 41154404, 2025). "SPARC was a common upregulated hub gene in our analysis and appears to originate predominantly from the tumor stroma." (PMID 40872572, 2025). "Targeting SPARC proteins in the tumor microenvironment using albumin to reduce allergic reactions and increase intra‐tumor drug concentrations." (PMID 40135802, 2025). "Endogenous SPARC performs tumor-suppressive functions in PDAC cells by inhibiting malignant phenotypes." (PMID 40619414, 2025). "Another approach to activate the immune microenvironment of ECM3 BC is to directly target SPARC secretion at its source in tumor cells." (PMID 40890836, 2025). "In the tumor microenvironment, SPARC is secreted by tumor cells as well as by surrounding fibroblasts, cancer-associated fibroblasts, infiltrating leukocytes, and endothelial cells." (PMID 40943659, 2025). "To explore this mechanism, we selected PV-1, a tumor endothelial cell-specific marker, along with Caveolin-1, which is known to facilitate albumin endocytosis by endothelial cells, and SPARC, a protein that specifically binds to albumin." (PMID 40429837, 2025). "LHNP exploits the enhanced permeability and retention (EPR) effect and albumin-mediated transport (via gp60 and SPARC interactions) to accumulate in tumor tissues." (PMID 40733107, 2025). "In PC, SPARC is often subject to abnormal methylation and is involved in tumor-stromal interactions." (PMID 40619414, 2025). "SPARC, as an exocrine protein, is bound to play a more important role in the tumour microenvironment, which is worthy of further exploration." (PMID 40415238, 2025). "The progression of OSF toward malignancy is associated with the upregulation of SPARC, activation of MMP9, and overexpression of ITGA5, promoting ECM degradation, facilitating cell invasion, and driving tumor progression." (PMID 39865173, 2025). "Theses 13 genes (e.g., COL1A1, POSTN, ASPN, PDGFRA, MUC4, SPARC), implicated notably in EMT and cancer progression, were found to be highly expressed in depth of tumor ID15 and ID08, near the invasive margin." (PMID 40076457, 2025). "Additionally, the study demonstrated that elevated expression of Secreted Protein Acidic and Rich in Cysteine (SPARC) in the tumor stroma is associated with improved survival rates, supporting the hypothesis that targeting stromal components is essential for maximizing treatment efficacy." (PMID 40427222, 2025). "Under 5‐FU treatment, the tumour volume of the mice in the SPARC overexpression group was significantly larger than that in the control group, and this phenomenon was inhibited by the HK2 inhibitor 2‐DG." (PMID 40415238, 2025).
tumor (continued). "SPARC plays a complex role in lymphoid malignancies, acting either as a tumor suppressor by inhibiting cell proliferation and inducing apoptosis, or as a tumor promoter by enhancing extracellular matrix (ECM) remodeling, angiogenesis, and immune evasion." (PMID 40299416, 2025). "SPARC is believed to be a tumor progression biomarker because of its expression in neoplastic cells of primary PC samples from metastatic cases." (PMID 40001606, 2025). "The mRNA expression level of SPARC in TCGA dataset was also found to be higher in tumor as compared to normal." (PMID 40810390, 2025). "The existing liposome carriers have the problem of insufficient stability, while albumin can improve drug enrichment efficiency through the SPARC-mediated tumor uptake mechanism." (PMID 40871588, 2025). "As a nanoparticle albumin-bound formulation, nab-paclitaxel targets secreted protein acidic and rich in cysteine (SPARC) within the tumor stroma, reducing desmoplasia and enhancing vascular permeability—thereby improving gemcitabine delivery." (PMID 41040509, 2025). "In vivo a xenograft tumor model was constructed to verify the function of SPARC in 5‐FU chemoresistance." (PMID 40415238, 2025). "The system employs albumin nanoparticles loaded with gemcitabine, which exploit the SPARC protein and gp60 receptor mediated pathways for preferential tumor cell uptake." (PMID 41293424, 2025). "Accounting for 55–65% of plasma proteins, SA exhibits exceptional biocompatibility, prolonged circulation, and inherent tumor targeting via SPARC-mediated uptake." (PMID 40871588, 2025). "These phenomena suggest that SPARC plays different roles in tumor progression across different tumor cell types and acts via different signal transduction pathways." (PMID 39424639, 2024). "Our previous work showed that biologically active albumin nanoparticles can effectively target solid tumors via GP60 and SPARC pathways and can effectively inhibit tumor growth and prolong the survival time of tumor-bearing mice." (PMID 38323081, 2024). "It then associates with FcRn systemically and in tumor tissue, more specifically to GP60, and then binds tightly to SPARC." (PMID 39697343, 2024). "GP60 is expressed on vascular endothelial cells and enables albumin to cross the vascular endothelial cell layer, and SPARC is overexpressed in many types of tumor cells, while it is minimally expressed in normal tissue cells." (PMID 38323081, 2024). "Their meticulous cDNA microarray analysis revealed a consistent upregulation of SPARC during the transition from normal mucosa to tumor tissue, which was further validated through immunohistochemistry." (PMID 38946720, 2024). "Albumin drug delivery systems constructed on the basis of the albumin–GP60 interaction and albumin–SPARC interaction can target tumor tissue or cells via GP60 and SPARC pathways." (PMID 38323081, 2024). "In this case, SON-1010 bound to albumin is pulled through the endothelial cells into the TME and is retained in that space by extracellular SPARC, giving the IL-12 extended time to activate the local immune response for better tumor control." (PMID 39697343, 2024). "We use relative SPARC expression as one of the ways to select tumor indications for studies in humans." (PMID 39697343, 2024). "In tumorigenesis, SPARC is expressed in tumor cells and surrounding stromal fibroblasts, sometimes designated as tumor-associated fibroblasts." (PMID 38347494, 2024). "Drug carriers constructed based on the albumin–SPARC interaction can reach the tumor tissue or cells more efficiently." (PMID 38323081, 2024). "Clinically, LCN2 expression in GC negatively correlates with tumor grade, poor prognosis, SPARC expression, and c-Jun expression." (PMID 39424639, 2024). "nab-paclitaxel can bind to tumor cells via secreted protein acidic and rich in cysteine (SPARC) and enter tumor cells, releasing drugs that kill tumor cells." (PMID 39134689, 2024).
tumor (continued). "Consistently, RT-qPCR and western blotting in our cohort showed significant overexpression of SPARC and c-Jun in GC tissues compared to that in paired non-tumor tissues, and a positive correlation was observed between SPARC expression and GC grade." (PMID 39424639, 2024). "Despite SPARC’s multifaceted roles across various cancer types, it's undeniable that modifying its expression and activity can significantly alter tumor and cellular characteristics." (PMID 38650694, 2024). "Albumin nanoparticles tend to accumulate in NSCLC due to the presence of GP-60 receptors in tumoral blood vessels and the overexpression of SPARC proteins in the tumour." (PMID 39771562, 2024). "Tumour tissues overexpress secreted protein acidic and rich in cysteine (SPARC), which functions similarly to albumin receptors by selectively binding albumin and accumulating it in tumour cells." (PMID 39548502, 2024). "We found that SPARC was significantly upregulated in GC tissues compared to that in paired adjacent non-tumor tissues, and that its expression levels correlated positively with higher tumor grade in patients with GC from TCGA cohort." (PMID 39424639, 2024). "Through these receptors, albumin nanoparticles are internalised to the tumour interstitium, where they bind to secreted acidic proteins rich in cysteine (SPARC) that are overexpressed in many tumours, such as lung, breast, and pancreatic carcinomas." (PMID 39771562, 2024). "Produced and secreted by various cell types, spanning from cancer cells to stromal and immune cells, SPARC influences the tumor microenvironment in several ways." (PMID 38650694, 2024). "Contrary to these observations, SPARC can also delay tumor growth and metastasis in certain cancer types." (PMID 39424639, 2024). "Using data from 523 patients with HNSCC from TCGA, we found a significant correlation between the expression of the Epi_C1_SPARC cluster in tumor tissues and overall survival (OS); higher expression was indicative of poorer prognosis." (PMID 38720887, 2024). "The divergent actions of SPARC also led to questions regarding its complexity and how it regulates tumor growth." (PMID 39424639, 2024). "The strong affinity between SPARC and albumin contributed to the enhanced utilization of nab-paclitaxel by tumor cells, thereby potentially augmenting the therapeutic efficacy." (PMID 38914827, 2024). "SPARC is covered in interactions between the tumor and stroma and influences cancer growth by influencing tumor invasion." (PMID 37577749, 2023). "Here, we analyzed by immunohistochemistry the prognostic value of tumor and stromal cell SPARC expression in 148 patients with non‐metastatic TNBC and long follow‐up (median: 5.4 years)." (PMID 36346290, 2023). "In conclusion, SPARC is involved in tumor invasion, metastasis, immunosuppression, cancer cell stemness, and tumor angiogenesis, eventually impacting patient survival." (PMID 37509139, 2023). "SPARC is a tumor suppressor in some studies and a tumor promoter in others, depending on tissue and cell type." (PMID 36999020, 2023). "Both biomarkers, SPARC and FAP, are associated with tumor progression and metastasis and predict a poor outcome in patients with PDAC." (PMID 38136299, 2023). "In the cells of tumor, the expression of SPARC protein is related to the clinical response rate of nab‐paclitaxel." (PMID 37334881, 2023). "SPARC is an extracellular glycoprotein that is abnormally overexpressed in solid cancers, including brain tumors, and acts as a promoter of tumor proliferation and metastasis." (PMID 36945032, 2023). "SPARC-null mice are resistant to UV-induced SCC induction, suggesting a tumor-promoting role of SPARC in the skin." (PMID 37762344, 2023). "PTX is encapsulated in albumin-based nanoparticles, accumulated in tumors through receptor-mediated transcytosis, and bound to the overexpressed SPARC protein on the tumor surface." (PMID 37836018, 2023).
tumor (continued). "It is also known that PI3K-AKT-mTOR signaling pathway activation via CAF-derived secretion, such as through CXCL12, VCAM1, IL-22, CXCL5, HGF, and SPARC, induces tumor proliferation, migration, and stemness." (PMID 37264057, 2023). "As SPARC was expressed in the tumor and stromal compartments, its prognostic value was then evaluated." (PMID 36346290, 2023). "It has been reported that the albumin-binding proteins in the tumor endothelium (gp60 receptor, albondin) and secreted SPARC protein in the tumor stroma have a high binding affinity for albumin, thereby enhancing the retention of albumin in the tumor region." (PMID 36614294, 2023). "Neoadjuvant chemoradiotherapy can improve the tumor resection rate and SPARC was found to be its central gene." (PMID 37577749, 2023). "In 80% of samples, SPARC expression was lower in the adjacent normal breast tissue than in the tumor tissue." (PMID 36346290, 2023). "Secreted protein acidic and rich in cysteine (SPARC) can regulate glucose metabolism in tumor cells, and such a process is related to HK2." (PMID 38076208, 2023). "We then showed that fibroblast‐secreted SPARC had a tumor‐promoting role by inhibiting TNBC cell adhesion and stimulating their motility and invasiveness." (PMID 36346290, 2023). "SPARC shows potential as a prognostic indicator of tumor recurrence or progression during prostate cancer theranostics but is affected by hematuria." (PMID 37577749, 2023). "Activation of insulin signalling, inhibition of TGF‐β signalling, or modulation of ECM levels via SPARC, Rab10 or Collagen IV in the fat body, is able to rescue tissue wasting in the presence of tumour." (PMID 38014610, 2023). "MDA‐MB‐231 tumor spheroid invasiveness at day 3 was 3.4‐fold higher in the presence of HMF CM than SPARC‐immunodepleted CM (P < .01)." (PMID 36346290, 2023). "Here, we showed that in TNBC, SPARC is expressed in both tumor and stromal cells, and that its expression in CAFs independently predicts RFS in patients with TNBC." (PMID 36346290, 2023). "Once nab-paclitaxel is in the extravascular space, it can accumulate inside the tumor through the interaction between SPARC (secreted protein acidic and rich in cysteine) and albumin." (PMID 37509639, 2023). "Next, we will investigate the structure and function of vessels under conditions of blocking or upregulating caveolin-1, and the corresponding SPARC expression, which would shed light on the role of the caveolin-SPARC pathway in tumor angiogenesis scenario." (PMID 37528424, 2023). "We found that alternatively activated macrophages utilize stabilin-1 for the efficient clearance of soluble component of tumor extracellular matrix SPARC." (PMID 36960065, 2023). "Each tumor was extracted 1 h post-injection of each fluorescent probe, and immunostaining was performed to observe the location of the SPARC protein." (PMID 36614294, 2023). "Previously, SPARC has been proposed as a tumor-suppressor protein that can induce apoptosis and inhibit angiogenesis by reducing VEGF expression." (PMID 37719007, 2023). "In xenograft models SPARC inhibited angiogenesis, resulting in reduced tumor growth, which was accompanied by significant alterations in the ECM texture." (PMID 37762344, 2023). "Although the tumor burden was diminished under SoC treatment, the mRNA expression levels of SPARC and FAP were unaffected in corresponding samples of the treatment groups compared to vehicle-treated controls." (PMID 38136299, 2023). "In contrast, several studies indicate a clearly opposite tumor suppressive effect of SPARC in several cancer types." (PMID 37762344, 2023). "SPARC makes a contribution to the immunosuppressive microenvironment, which drives the phenotypic plasticity of tumor cells to promote their aggressiveness and invasion." (PMID 37509139, 2023). "The capacity of HMF‐secreted SPARC to enhance MDA‐MB‐231 cell invasion was confirmed in a tumor spheroid assay." (PMID 36346290, 2023).